LCN2 (lipocalin 2)
Diseases named in the same sentence as LCN2 in open-access papers (continued):
Sharing a sentence is not in itself a finding about the gene and the disease.
cancer (continued). "Lipocalin‐2 (LCN2)—a secretory protein transporting various lipophilic molecules such as steroids, lipopolysaccharides, iron, and fatty acids—is overexpressed in cancer cells within the CSF of patients with leptomeningeal metastasis from breast or lung cancer." (PMID 40719284, 2025). "Functionally, they showed that LCN2 expression was induced by pro-inflammatory cytokines and promoted cancer cell growth in a mouse model of LM." (PMID 41303420, 2025). "The protein LCN2 is associated with immune reactions via ferric ion (Fe3+) transportation, and a recent study has reported that the expression of LCN2 was relevant to the activation of NF-κB in cancer cells." (PMID 40502700, 2025). "Chi Y, Remsik J, Kiseliovas V, Derderian C, Sener U, Alghader M, Saadeh F, Nikishina K, Bale T, Iacobuzio-Donahue C, Thomas T, Pe'er D, Mazutis L, Boire A (2020) Cancer cells deploy lipocalin-2 to collect limiting iron in leptomeningeal metastasis." (PMID 40100294, 2025). "Yang and coworkers linked LCN2 expression in TNBC cells to the induction of VEGF, promoting neovascularization and vascular permeability, thus playing an important role in cancer metastasis." (PMID 41303420, 2025). "Lipocalin-2 (LCN2), a pleiotropic protein implicated in tumorigenesis and cancer progression, has been associated with multiple malignancies." (PMID 40211270, 2025). "Together, our Herceptin-liposomal formulation encapsulating siRNA against lipocalin-2 (LCN2) offers a clinically translatable approach for HER2-positive cancers by combining targeted therapy with gene silencing." (PMID 40732340, 2025). "Cancer cells can also upregulate lipocalin-2 and its receptor to scavenge scarce iron, sustaining growth in iron-poor niches." (PMID 41190142, 2025). "Cancer cells secrete LCN2 into the CSF to sequester iron from CSF macrophage, thereby impairing macrophage function and supporting metastatic growth." (PMID 40100294, 2025). "These comprehensive analyses revealed that LCN2 knockdown significantly altered gene expression, disrupting multiple cancer-related pathways." (PMID 40732340, 2025). "It has been shown to be overexpressed in colorectal neoplasms, and higher circulating LCN2 concentrations have been observed in CRC patients as compared to cancer‐free controls." (PMID 39511728, 2025). "In particular, clusters 9, 10, 12, 13, 14, 16, 18, 19, 21, 26, 27, 28, 30, 34 and 35 not only expressed ductal cell markers (KRT19, MMP7, TSPAN8, SOX9 and LCN2), but also expressed cancer cell markers (MUC1 and PROM1)." (PMID 40362181, 2025). "NUPR1 can protect cancer cells from excess iron by inducing the expression of the iron-sequestering protein lipocalin-2 (LCN2)." (PMID 41429768, 2025). "Single-cell RNA-sequencing analysis of cerebrospinal fluid in patients with leptomeningeal metastases reveals that macrophages in the TME induce lipocalin-2 (LCN2) expression in cancer cells, which allows for enhanced iron uptake." (PMID 39188677, 2024). "This is regulated by the adipocytokine lipocalin 2 (LCN2), which released by macrophages, and its neutralization reverses iron elevation in cancer cells." (PMID 39201626, 2024). "A probable explanation is that LCN2 expression is potently stimulated by inflammation and all cancers have a strong inflammatory component or that it is upregulated as a compensatory mechanism in response to inflammation as an anti‐inflammatory." (PMID 38035773, 2024). "LCN2 also plays a role in cancer progression by breaking down the extracellular matrix and promoting metastasis." (PMID 38673873, 2024). "In this context, TAMs also express elevated levels of FPN and LCN2 for transporting iron to cancer cells." (PMID 39850877, 2024). "LCN2 has been increasingly identified for its significant role in modulating the response to radiotherapy and chemotherapy across various cancer types." (PMID 39188682, 2024). "Overexpression of LCN2 has been observed in various cancers, indicating its potential as a therapeutic target." (PMID 39850877, 2024).
cancer (continued). "LCN2 deficiency significantly altered the MAPK signaling pathway, which plays a crucial role in cancer progression." (PMID 39424639, 2024). "Overall, LCN2 is a key mediator of chemotherapy resistance across various cancers, warranting further research into its mechanisms and potential as a therapeutic target." (PMID 39188682, 2024). "Instead, they induce cancer cells within the CSF to upregulate the expression of LCN2 and its receptor SCL22A17." (PMID 39188682, 2024). "The role of LCN2 in the regulation of iron homeostasis is well documented in multiple studies and is a potent therapeutic target in cancers." (PMID 38673873, 2024). "S100A family genes and LCN2 have been shown to reprogram the epithelial phenotype and promote migration and invasion of cancer cells." (PMID 39003681, 2024). "Previous studies have demonstrated that M2 phenotype macrophages exhibit increased phagocytic activity, efficiently recycle iron, produce and secrete the iron transporter LCN2 into their microenvironment, thereby supplying more iron to cancer cells." (PMID 39850877, 2024). "NF-κB is also activated in inflamed tissues and also upregulates LCN2 in cancer cells, leading to sustained inflammation." (PMID 39839775, 2024). "The interaction between LCN2 and catechol activates iron trafficking, regulates iron-responsive genes, and contributes to cancer progression." (PMID 38673873, 2024). "LCN2-activated astrocytes in brain metastasis are induced by various cytokines and growth factors secreted by cancer cells." (PMID 39188682, 2024). "Although iron chelators and anti-MMP9 moieties have continued to be studied separately, there is a need to further evaluate anti-Lcn-2 antibodies in clinical trials, and in combination with current therapies for specific cancer subtypes." (PMID 37958332, 2023). "During CAC, Lcn2 has been described to be upregulated in neutrophils and was found in high concentrations in the plasma and the cerebrospinal fluid of cancer patients correlating with increased mortality." (PMID 37222464, 2023). "Guo and colleagues showed that the siRNA silencing of Lcn-2 in a TNBC model inhibited angiogenesis in vivo and in vitro, while in a similar study on IBC, the depletion of Lcn-2 in cell cultures reduced invasion, migration, and the cancer stem cell population." (PMID 37958332, 2023). "In mammals, a study using a mouse model of leptomeningeal metastasis showed that cancer cells use lipocalin 2 to collect iron." (PMID 36973755, 2023). "Despite being expressed at low levels in most human tissues, LCN-2 is abundant in more aggressive forms of cancer, such as breast, pancreatic, thyroid, ovarian, colon, and bile duct cancers." (PMID 38058391, 2023). "We also found that N2 neutrophils promote brain metastasis by secreting G-CSF-mediated LCN2, which enhances the cancer stemness of brain metastatic cells." (PMID 37174093, 2023). "Elevated circulating LCN-2 has been found in many types of cancer and promotes malignant development in cancer patients." (PMID 37006254, 2023). "Since Lcn2 has been described to be involved in several cachexia-affected organs as well as in cancer, its role during CAC becomes of interest." (PMID 37222464, 2023). "It was shown that macrophages provide signals that trigger Lcn-2 production by cancer cells, which, in turn, allows cancer cells to outcompete macrophages in acquiring iron by using Lcn-2 as alternative iron supply." (PMID 37958332, 2023). "Iron uptake in cancer cells is increased through the upregulation of Transferrin/Transferrin-receptor (Tf/TfR), and Lipocalin-2/Lipocalin-2 Receptor (Lcn-2/Lcn-2R) systems and also Divalent Metal Transporter-1 (DMT1)." (PMID 36986466, 2023). "Lipocalin 2 (LCN2), a multifunctional secretory protein identified as neutrophil gelatinase-associated lipocalin (NGAL), is expressed in various cancers, and depletion of NGAL expression reduced cell growth and proliferation and promoted cell apoptosis." (PMID 36978983, 2023).
cancer (continued). "The involvement of Lcn-2 in carcinogenesis has been studied using murine models, in human and murine cancer cell lines, and in patients." (PMID 37958332, 2023). "Next, we pretreated cancer cells with a gradient concentration of LCN2 and found that LCN2 promotes cancer cell sphere formation in a concentration-dependent manner." (PMID 37174093, 2023). "More specifically, in the following sections, we will focus on the macrophage-mediated regulation of Lcn-2 expression and the effect of Lcn-2 on macrophage polarization in cancer development and metastasis." (PMID 37958332, 2023). "We also found that N2 neutrophils promote brain metastasis by supporting cancer stemness through LCN2." (PMID 37174093, 2023). "Recent studies have shown that extracellular LCN2 enhances the stemness of cancer cells by elevating iron uptake." (PMID 37174093, 2023). "Lipocalin 2 (LCN2), a protein with antioxidant capacity, is upregulated under various cellular stress conditions, particularly in cancer." (PMID 36838613, 2023). "First and foremost it has been established that the substantial functioning of ADAM8 lies in the extracellular liberation of MMP-9 and LCN2, which are two key facilitators of cancer advancement in PDAC." (PMID 36910158, 2023). "Lipocalin-2 (Lcn-2), a secreted siderophore-binding glycoprotein that regulates iron homeostasis, is highly upregulated in various cancer types." (PMID 37958332, 2023). "In fact, both SERPINA3 and LCN2 were reported as both oncogenes and tumor suppressors in cancer, and their roles are likely to be tissue specific." (PMID 37408474, 2023). "Lipocalin-2 expression is correlated with tumorigenesis and thus considered as a biomarker in several subtypes of cancer." (PMID 37958332, 2023). "The heterodimer Lcn-2/MMP9 was shown to be elevated in patients suffering from different carcinomas." (PMID 37958332, 2023). "In vivo, they demonstrated that these cytokine-derived macrophages induce LCN2 expression by cancer cells." (PMID 35884845, 2022). "First, we demonstrate the essential function of ADAM8 in the extracellular release of MMP-9 and LCN2, two important mediators of cancer progression in PDAC." (PMID 35216088, 2022). "Lcn2 has been extensively reviewed in the literature regarding its relation to cancer, whereas interactions between siderophores and the immune system have not been as comprehensively studied." (PMID 35785195, 2022). "Taken together, these data suggest that LCN2 regulates protein expression related to cell survival and cancer progression mediated by NF-kB and STAT3 activation." (PMID 35470375, 2022). "Although we were able to show increased serum LCN2 level in preclinical models for cancer cachexia, there are several limitations to the current study." (PMID 36428623, 2022). "Previous studies have reported that LCN2 is involved in pathological disorders, especially in inflammation, metabolic disease, neurological disease, and cancers." (PMID 36428800, 2022). "The clinical validation of LCN2 as a biomarker for cancer cachexia was a preliminary study limited by the small sample size of only n = 6 for both cachectic and non-cachectic groups." (PMID 36428623, 2022). "LCN2 expression is negatively associated with EMT signaling, which has been reported in several cancer type." (PMID 35705840, 2022). "Altogether, these findings suggest that LCN2 in GC cells negatively induces the EMT phenotype which enhances cancer cell proliferation and invasion." (PMID 35705840, 2022). "The circulating LCN2 levels in these cancer patients were determined using a capture/reporter ELISA." (PMID 36428623, 2022). "Lipocalin‐2 (LCN2) is upregulated in various cancer types, while they are decreased in allergic and atopic state and this, also has been proposed as a cancer biomarker." (PMID 35344301, 2022). "LCN2 has been show to participate in the initiation, progression and metastasis of various cancer types." (PMID 36428800, 2022).
cancer (continued). "We identified several circulating biomarkers for cancer cachexia and confirmed that LCN2 is a promising biomarker for cancer cachexia in humans." (PMID 36428623, 2022). "During cancer progression, LCN2 expression is regulated in a variety of human epithelial cancers, including breast, ovarian, pancreatic, oral, lung, esophageal and CRC." (PMID 35470375, 2022). "The LCN2/SLC22A17 system is a high affinity iron system that supports cancer cell growth and is inhibited by iron chelation therapy." (PMID 35884845, 2022). "Studies of the past decades revealed that LCN2 plays an essential role in tumorigenesis of various cancers." (PMID 35053376, 2022). "LCN2 influences not only physiological biological processes but also the development and spread of various types of cancer." (PMID 35053376, 2022). "However, the role of LCN2 in inflammation-associated cancer remains unknown." (PMID 35470375, 2022). "LCN2 plays an essential role in normal physiology and disease, in several organs such as liver, renal, brain, muscle, and lung, including malignant tumors, and has been extensively studied as a biochemical marker." (PMID 36077676, 2022). "Although the functional role of LCN2 in cancer has been investigated, studies linking LCN2 to cancer as a driver of chronic inflammation are still lacking." (PMID 35470375, 2022). "They found that cancer cells in the CSF express the iron-binding protein lipocalin-2 (LCN2) and its receptor SCL22A17." (PMID 35884845, 2022). "Lipocalin (LCN) 2 (LCN2), a member of the lipocalin superfamily, plays an important role in oncogenesis and progression in various types of cancer." (PMID 35470375, 2022). "LCN2 has emerged as an upregulated protein in various types of cancers and has been identified as a potential therapeutic target in previous studies." (PMID 35705840, 2022). "Lipocalin 2 (LCN2) is an oncogene that has been widely studied in the field of cancer and cellular autophagy research." (PMID 35989326, 2022). "To investigate the role of LCN2 in cancer development driven by chronic inflammation, we analyzed the molecular mechanisms associated with cell survival and apoptosis that are downstream of the NF-kB/STAT3 pathway by Western blotting." (PMID 35470375, 2022). "To confirm if LCN2 can be used as a potential biomarker for diagnosing human cancer cachexia, we examined LCN2 levels in serum samples from patients with different cancers." (PMID 36428623, 2022). "Cancer cells of BC‐LM and LC‐LM make use of iron collection system LCN2/SLC22A17 to outcompete the macrophages, the major iron‐utilising cells, for sparse environmental iron, which promotes cancer cells growth and evades immune responses." (PMID 35678121, 2022). "As such, both CLDN1 and LCN2 have been suggested to be involved in cancer dedifferentiation, future work is needed to establish the mechanistic basis of their actions—especially in the context of obese environments." (PMID 35013251, 2022). "As a small-secreted glycoprotein, Lipocalin 2 (LCN2) acts as an innate immune protein and regulates inflammatory conditions and is involved in various types of malignant tumours." (PMID 34601488, 2021). "One more emerging role of LCN2 in cancer pathogenesis is related to its first known function, which is called iron transport." (PMID 33799862, 2021). "In this context, Liu and colleagues showed in cancer cells that NUPR1 can regulate iron metabolism through transcriptional activation of lipocalin 2 (LCN2) and protect the cells from ferroptosis." (PMID 34359572, 2021). "Once synthesized within the cancer cells, LCN2 is released into the extracellular matrix where it forms LCN2-catecholate-Fe3+ (LCF) complex." (PMID 34588926, 2021). "We further reported that depletion of LCN2 in IBC cell cultures reduced features associated with aggressiveness in vitro, including migration, invasion, and cancer stem cell populations." (PMID 34342930, 2021).
cancer (continued). "LCN2 silencing also significantly reduced the percentage of cancer stem cell populations in LCN2‐silenced IBC cells relative to control, as shown by reductions in primary and secondary mammosphere formation efficiency and CD44+CD24− cell subpopulations." (PMID 34342930, 2021). "Since LCN2 is demonstrated to mediate appetite and fat metabolism, two important components of cancer cachexia, our lab sought to address if LCN2 influences any of the signs or symptoms of cancer cachexia." (PMID 34439145, 2021). "As it can be seen, findings on LCN2 in cancer portray its paradoxical effects on individual cancer types that need to be further investigated before any kind of therapy targeting LCN2 is planned." (PMID 33799862, 2021). "As LCN2 plays a pivotal role in cancer, targeting this protein offers a novel opportunity to develop a specific IBC treatment drug." (PMID 34445288, 2021). "Abnormal expression of LCN2 plays an extremely important role in the epithelial-to-mesenchymal transition process, angiogenesis, and cell migration and invasion in several cancers by involving multiple signaling pathways." (PMID 33407508, 2021). "The expression of two iron metabolic genes (FPN and LCN2) was selectively knocked down in cancer cells by Cas13a or microRNA controlled by a NF-κB-specific promoter." (PMID 34493724, 2021). "Here, we proposed Lipocalin-2 (LCN2)—a secreted glycoprotein aberrantly abundant in different cancers—as a plausible target for IBC." (PMID 34445288, 2021). "Further digging detail into the clinic-pathological variable in the METABRIC cohort, our data explained that the LCN2 gene expression was higher for advanced cancer staging in the METABRIC cohort, and the trend was observed in the TCGA cohort." (PMID 34072157, 2021). "LCN2 is dysregulated in multiple diseases like cancers in which it facilitates tumorigenesis by promoting survival, growth, and metastasis." (PMID 34029211, 2021). "We aimed to investigate the effect of LCN2 on apoptosis that influences the pathogenetic process of metabolic diseases and cancer." (PMID 34903175, 2021). "In fact, in these settings, TAMs do not (or not only) directly provide cancer cells with iron, but produce cytokines that stimulate lipocalin-2 expression in cancer cells." (PMID 33804198, 2021). "What makes LCN2 more interesting to study is the fact that it is overexpressed in HCC development induced by chronic NASH, which is one of the primary causes of cancer-related deaths." (PMID 33799862, 2021). "LCN2 has also been shown to promote malignant progression in many cancer types and can serve as a biomarker for cancer patients." (PMID 32153594, 2020). "Neutrophils and Type 17 T helper cell were two immune cell types most strongly correlated with LCN2 expression across 32 cancer types." (PMID 33425761, 2020). "An interrogation of The Cancer Genome Atlas (TCGA) data portal showed that several cancers have significantly altered expression of LCN2 compared to normal tissue, suggesting LCN2’s potential as a prognostic biomarker." (PMID 32575507, 2020). "Taking these facts together, LCN2 was not only a marker of immune infiltration and poor prognosis, but also a candidate and promising therapeutic target for cancers." (PMID 33425761, 2020). "This study was designed and performed according to the flow chart The findings implied that LCN2 influenced the prognosis of cancer patients, probably through its interaction with TIICs." (PMID 33425761, 2020). "Lipocalin 2 (LCN2) is known to play important roles in cancer initiation, progression, and treatment responses." (PMID 33604288, 2020). "We firstly checked the genetic alterations of LCN2 genes in cancer patients using cBioPortal database." (PMID 33425761, 2020). "The results revealed that the expression of LCN2 was correlated with the infiltration levels of cancers." (PMID 33425761, 2020).